CD4 (CD4 molecule)
Diseases named in the same sentence as CD4 in open-access papers (continued):
Sharing a sentence is not in itself a finding about the gene and the disease.
tumor (continued). "Capacity to build multicytokine CD4+ and CD8+ T cell response against epitopes in TERT1, TERT6, and TERT8 (specifically, TERT6 and TERT8) discriminated mice that were able to restrict tumor growth." (PMID 32570805, 2020). "Moreover, we show that the entry of cytotoxic lymphocytes, such as CD4+ and CD8+ TEFF into the tumor tissue is compromised, and that, following recruitment, these effectors undergo exhaustion." (PMID 32182707, 2020). "Given that pro-inflammatory responses are thought to be helpful in the suppressive tumor environment, deletion of PTPN2 in CD4 T cells could enhance CD8 T cell-mediated tumor elimination and might also inhibit the development of Tregs." (PMID 33425916, 2020). "We next evaluated multifunctional CD4+ and CD8+ T cells capable of simultaneously producing multiple effector Th1 cytokines and cytotoxic markers (IFN-γ, TNF-α, IL-2, and CD107a) because these cell types are strong effectors in tumor environments." (PMID 32486094, 2020). "CD4 and CD8 T cell tumor infiltration driven by HER2-dendritic cells improved survival of BC mice." (PMID 32296631, 2020). "In our current study, we uncovered that the pre-BCG tumor tissues of responders were presented with higher densities of CD8+PD-1+ as well as non-Treg CD4+FOXP3- T cells comparing with those of the non-responders." (PMID 33584702, 2020). "Indeed, the TNC knockout tumours had more CD4+ and CD8+ TIL cells and more activated cytotoxic T cells (IFNγ+CD4+ and IFNγ+CD8+) in their TILs than the control tumours." (PMID 32732922, 2020). "Therefore, the proportions of CD8+ IFN-γ+ CTLs and CD4+ IFN-γ+ Th1 cells in draining lymph nodes (dLNs), spleens and tumor tissues were detected by flow cytometry." (PMID 30925926, 2019). "Our results revealed that tumor Sdc-1 silencing promotes the proportion of Th1 (IFN-γ+CD4+) subset of non-IBC patients when stimulated with the secretome of Sdc-1-silenced SUM-149 cells but not in direct co-culture, as compared to negative control." (PMID 31145753, 2019). "In order to assess the correlation between the number of predicted neoantigens and tumor infiltrating immune cells in each HCC patient, heat maps were generated using expression level values of genes characterizing effector (CD4+ and CD8+ T cells) and regulatory (Tregs and MDSC) cells." (PMID 31756926, 2019). "In addition, we have found that high expression of CXCR3 protein was closely correlated with the increased recruitment of CD4+, CD8+ tumor infiltrating lymphocytes (TILs), and dendritic cells in our previous study." (PMID 31240220, 2019). "We further investigated tumor-infiltrated immune cells in the tumor microenvironment, and found a significant increase of CD45+ cells, and CD8+ T cells but not CD4+ T cells in the tumor tissues after β-lap treatment." (PMID 31324798, 2019). "Flow cytometry analysis of tumors excised from the mice at the end of treatment revealed that the populations of tumor-infiltrated CD45+CD8+ T-cells and CD45+CD4+ T-cells increased after Itga2 knockdown, while the population of CD11b+Gr1+ myeloid cells decreased." (PMID 31818309, 2019). "Although both editing-high and -low tumor groups were similar for overall lymphocytic infiltration, the editing-high tumors had significantly more T cells as well as various T cell subtypes (CD8+, CD4+, T-reg, and gamma delta T; fold changes of 1.08–1.67)." (PMID 31717692, 2019). "Such interaction mediated rejection of MHC II negative myelomas, thereby demonstrating tumor cell killing by inflammatory macrophages as a consequence of CD4+ Th1 cell mediated TAM instruction." (PMID 30853959, 2019). "Increased expression of these immune checkpoint receptors in CD4+ and CD8+ T cells of HNSCC tumor bearing Stat4−/− mice demonstrate the requirement for STAT4 in the inhibition of immunosuppressive T cell pathways and initiation of an appropriate immune response against metastatic HNSCC." (PMID 32010142, 2019).
tumor (continued). "Thus, CD4+ and CD8+ blood T-cell clones were enriched in the corresponding tumor microenvironment of the same patient." (PMID 31275310, 2019). "In agreement with the effect on tumor regression, treatment with the anti-PD-1-antibody after the knockdown of Hat1 led to a further decrease in tumor growth and an increase in CD45+CD8+ and CD45+CD4+ T cell infiltration, but a greater decrease in CD11b+Gr1+ myeloid cells in tumors." (PMID 30709380, 2019). "Mice lacking H4R show reduced tumor growth and percentage of CD4+ tumor-infiltrating T cells together with increased infiltration of natural killer (NK) cells." (PMID 31231212, 2019). "Interestingly, the tumor infiltrate of P2X7 null bearing mice treated with A740003 was characterized by increased CD4+ levels and decreased expression of CD73 on both Treg and Teff cells, possibly due to factors released by tumor cells following P2X7 blockade." (PMID 30655604, 2019). "Crosstalk between HRS cells and CD4-positive T cells is mediated primarily by the CD40-CD40 ligand interaction, leading to the activation of the NF-kB pathway, which has a crucial role in promoting tumor growth and disease progression." (PMID 31694167, 2019). "Comparing these non-ablated malignant liver lesions removed after RFA to lesions from mCRC patients with surgery only, significantly lower CD4+ cell counts in the tumor center as well as decreased numbers of CD8+ and CD4+ cells at the tumor border were observed for the RFA + surgery group." (PMID 31803175, 2019). "We quantitated the total of CD4+ T cells infiltrating each tumor, and found that G4 showed the highest percentage, albeit not statistically different from G1 (p ≥ 0.05)." (PMID 31762937, 2019). "Tumor-infiltrating phagocytes, including DCs, can engulf these extracellular antigens and typically process and present antigenic peptides via MHC class II for CD4 + T helper cell activation through the endosomal pathway." (PMID 31664044, 2019). "The percentages of total tumor-infiltrating CD4+ T cells also did not vary among the different treatment groups." (PMID 31747946, 2019). "The OxLDL-induced and SYK-mediated autophagy facilitates surface expression of MHCII and CD4+ T cells activation; thereby, SYK may enhance anti-tumor immunotherapy effects via a autophagy-mediated adaptive immune responses." (PMID 30678689, 2019). "Tumours harvested 24hr post last HKMTI-1-005 dose had significantly more effector CD8+T cells (p=.03), natural killer (NK) cells (p<.0001) and dendritic cells (DCs, p=.02), and less naïve CD8+T cells (p=.02) and immunosuppressive CD4+Tregs (p=.02)." (PMID 31591445, 2019). "Autologous whole tumor antigens offer an unparalleled advantage as they allow DCs to process and present a broad range of tumor-associated antigens to stimulate strong, polyclonal, and long-term memory CD4+ and CD8+ T cell responses, potentially preventing tumor immune escape." (PMID 31886313, 2019). "Pericytes generally support leukocyte transmigration into interstitial tissue but not CD4 T cell recruitment in the tumor microenvironment." (PMID 31205449, 2019). "In contrast, based on liver weight and Ki67-positive area, an anti-CD4 Ab did not alter the anti-tumor effect." (PMID 31105882, 2019). "Our previous work demonstrated that the E7-specific fusion protein vaccine PE-E7-K3 (PEK) was able to enhance the E7-specific immunity of both CD4 and CD8 T cells by targeting the HPV-16 E7 oncoprotein, generating potent E7-specific anti-tumor effects against impalpable pulmonary tumor nodules." (PMID 31546897, 2019). "Strikingly, systemic treatment of MC38 tumor bearing mice with a mouse-specific CD39 ASO potently suppressed CD39 protein expression on tumor infiltrating CD4+ Tregs and TAMs, but not on CD8+ T cells." (PMID 30871609, 2019). "CD4+ and CD8+ T cells accumulated around the margin of the overt SOX10+ Melan A+ ITM but were largely excluded from the tumor centre." (PMID 31885869, 2019).
tumor (continued). "Our data provide novel findings that HKP1 kinase activity is critical in conferring suppressive functions of HPK1 in a wide range of immune cells including CD4+, CD8+, DC, NK to Tregs, and inactivation of kinase domain was sufficient to elicit robust anti-tumor immune responses." (PMID 30913212, 2019). "Immunofluorescence staining results demonstrate that the increase of EpCAM+ CD4+ T cells is also observed in tumor tissues, rather than para-cancerous tissues." (PMID 31354723, 2019). "Moreover, in the ypCR group, CD4+ and CD8+ lymphocytes tumor infiltration was significantly higher than in yPPD group (P < 0.0001 and 0.0006, respectively)." (PMID 31429521, 2019). "Furthermore, imaging techniques and histological examination showed that the combination induced strong local necrosis, followed by an increase in the infiltration of CD4+ and CD8+ immune cells into the tumor parenchymal tissue." (PMID 30670061, 2019). "Contributions of activated CD4 T cells to anti-tumor immunity can be more than just providing the help to CTLs, but also include activation of NK cells and macrophages through IFN-γ, modulation of tumor stroma and angiogenesis or direct cytolytic effects." (PMID 31143179, 2019). "The better antitumor response correlated with increased tumor-specific CD8+ T cells and NK cells, but not CD4+ Tregs, in the irradiated tumor and in lymphoid organs." (PMID 30808414, 2019). "Rather than cytokines, NPs used in cancer therapy can carry tumor antigens to activate MФs and CD4+/CD8+ cytotoxic T cells against the tumor." (PMID 31744137, 2019). "Nonetheless, the role of CD4+ T cells in Bregs differentiation in the tumor microenvironment has not been addressed." (PMID 31300052, 2019). "Next, we assessed the size and cell composition of IAs by counting cells of 6 different sub-types (all tumor cells, HLA+ tumor cells, CD3+, CD4+ FOXP3+, CD8+PD1+, CD20+ cells) and calculated counts of each of these subpopulations relative to the number of total tumor cells in IAs." (PMID 31166985, 2019). "VISTA expression significantly decreased the number of CD8+ T cells at the tumour site but had no obvious difference on the number of CD4+ T cells." (PMID 30382166, 2019). "Previously, tumor cell–specific miR-142-5p expression has been shown to promote tumor immune evasion through inhibition of phosphatase tensin homolog (PTEN), leading to downstream upregulation of PD-L1, restricting CD4+ T cell antitumor immunity, or inducing cancer stem cell–like properties." (PMID 30741720, 2019). "Intravenous administration of an IL-18-expressing attenuated S. Typhimurium strain inhibited primary tumor growth in mice, induced massive leukocyte infiltration (mainly granulocytes), and increased NK and CD4+ T cell but not CD8+ T-cell recruitment." (PMID 31827064, 2019). "Nevertheless, class II HER2-DC1 vaccine failed to delay tumor growth in the absence of CD4+ T cells." (PMID 31475002, 2019). "Absence of CD4+ T cells negated the tumor-protective effect of DC depletion, suggesting that the protection afforded by DC ablation was CD4+ T-cell dependent." (PMID 30926808, 2019). "However, although traditional Tregs including CD4+ Tregs and CD8+ Tregs, both αβT cell types, have been extensively studied, much less is known about γδ T cells in tumor immunity." (PMID 31064389, 2019). "In stark contrast, this pattern was absent (Myd88, Cd4, Tlr9, Ly96) in tumor-bearing and/or –resected mice or reversed, in one case (C3)." (PMID 31019214, 2019). "Furthermore, the ratio between CD4+ and CD8+ T cells has an effect on the anti-tumor activity of CART cells." (PMID 31835562, 2019). "Overall, the contribution of peptide-HLA stability to the selection and sensitivity of anti-tumor CD4+ clones should not be overlooked." (PMID 31619516, 2019).
tumor (continued). "Also, it effectively increased the ovalbumin-specific CD8+ T cell and CD4+ T cell population and induced an ovalbumin-specific CTL response against the graft of ovalbumin-expressing EG7 tumor cells in the immunized mice." (PMID 31386690, 2019). "None of the immunized mice showed tumor growth, and the mice were protected beyond day 22 post-tumor challenge independently of the presence of CD4 T-helper cells." (PMID 31333674, 2019). "Not surprisingly, increasing evidence suggests that the presence, location and density of both CD4+ and CD8+ lymphocytes in the tumor microenvironment of patients are primary drivers for productive anti-tumor immune responses and are predictors of overall survival 11-16." (PMID 31754392, 2019). "Thus, in addition to the direct cytotoxic effect on tumor cells, D2C7-IT generates a secondary CD4+ and CD8+ T cell immune response." (PMID 31142380, 2019). "Furthermore, combined treatment with anti-PD-1 and anti-CTLA-4 antibodies produced higher CD4+ T cell, CD8+ T cell and DC infiltration into the tumor." (PMID 31291357, 2019). "Similarly, IL-24 mRNA expression in tumor-infiltrating CD4+ and CD8+ T cells was also remarkably reduced when compared with those from non-tumor tissue (Mann-Whitney tests, all P < 0.0001)." (PMID 31921658, 2019). "Both CD4+ and CD8+ T cell depletion significantly reversed the anti-tumor effect of CTX + IL-1α-NP, and CD8+ T cell depletion was significantly more effective than CD4+ T cell depletion at reversing the anti-tumor effect of CTX + IL-1α-NP." (PMID 30890189, 2019). "Accordingly, in this scenario, the tumor-derived cDC1 primes CD8 T cells while tumor-derived cDC2 activates CD4 T cells in the first step of the CTL priming process and then in the second step, the activated CD4 T cells licenses a LN-resident cDC1 to relay the help for CTLs." (PMID 31143179, 2019). "In contrast, the depletion of CD4+ population had a minimal impact on the tumour growth kinetics that was not statistically significant." (PMID 31906092, 2019). "Notably, we found that cells expressing CTLA-4, the first approved checkpoint blockade target, displayed a generally low frequency (<20%) in both CD4 and CD8 T cell populations in the tumor and peripheral blood across eight cancer types." (PMID 31709176, 2019). "Tumor vaccines stimulate the patients’ immune system, especially the response of specific CD8+ T cells; however, interferon gamma (IFNγ) produced by CD8+ and Th1 CD4+ cells regulate the expression of PD-L1." (PMID 31443694, 2019). "CD4+ T helper type 1 (Th1) cells secrete the cytokine interferon (IFN)-γ and affect tumor growth by targeting the tumor microenvironment (TME), antigen presentation through major histocompatibility complex (MHC) class I and MHC class II, and other immune cells." (PMID 31801070, 2019). "Therefore, we sought to assess the degree of infiltrating lymphocytes in our ODI and found a dramatic reduction of T lymphocytes (CD3+cells), TH CD4+ T cells, and particularly of cytotoxic CD8+ T cells, in tumours compared to preinvasive lesions." (PMID 31439856, 2019). "The main sources of IFNγ are CD4+ and CD8+ T cells in the tumor microenvironment, respectively." (PMID 30886199, 2019). "The number of CD8+ T and CD4+ T cells significantly greater in the brains of mice implanted with FGL2KO tumor cells than in those implanted with Ctrl tumor cells, but this was not the case with NK or NKT cells." (PMID 30683885, 2019). "Moreover, islets of tumor rich of CD3+/CD8+ TILs show a high mRNA level of interferon γ (INF γ) and IL-2, secreted by CD4+ T-helper 1 cells and activated CD8+ T cells." (PMID 31096567, 2019). "Immunophenotyping of circulating CD4+ T helper cells drained from the tumor microenvironment of non-IBC and IBC patients." (PMID 31145753, 2019).
tumor (continued). "We next looked at the composition of infiltrating leukocyte subsets in the TME by flow cytometry and identified significant increases in the relative percentages of total T cells, CD4+ T cells, and NK cells among total CD45+ cells in HC-EMT6 tumors compared with controls by day 35 of tumor growth." (PMID 31139180, 2019). "Compared with the controls (vehicle or no treatment), SLR14 treatment induced a significant increase of tumor-infiltrating CD45+ leukocytes, including CD11b+ myeloid cells, CD8+ T cells, and NK1.1+ cells, whereas CD4+ cells or CD4+FoxP3+ T reg cells were significantly decreased (top)." (PMID 31601678, 2019). "We decided to investigate whether tumor produced LXR ligands can directly influence the function, differentiation and polarization of CD4+ T-cells." (PMID 31863071, 2019). "Mice without STAT3 in myeloid compartment of tumor stroma, including DCs and macrophages, present reduced numbers of tumor-infiltrating CD4+CD25+/FOXP3+/LAG3+ Tregs, along with an increase in CD8+ effector T-cells." (PMID 31480382, 2019). "Once more, CD4+ CAR T cells required longer conjugation for efficient killing of tumor cells regardless of the mechanism employed." (PMID 30875739, 2019). "CD4 + and CDS+ T cells that express CARs containing specific combinations of intracellular signaling domains can be used to increase persistence and anti-tumor activity of the infused CAR-expressing T cells." (PMID 30847027, 2019). "CD4+ T cells (Th1 cells) combined with IFN-γ signaling and tumor necrosis factor p55 receptor (TNFR1) signaling could arrest tumor growth and establish a state of tumor dormancy in an analyzing T antigen (Tag)-induced pancreatic cancer mouse model." (PMID 31297335, 2019). "The current data indicated that increased Notch receptors expression in GC patients might promote suppressive capacity of CD4+CD25+CD127dim/− Tregs, leading to the immunotolerance and reduced tumor rejection." (PMID 30988066, 2019). "As observed before, tumor-derived MDSC were more suppressive compared to their splenic counterparts, with the highest suppression seen in PMN-MDSC co-cultures, for both CD8+ and CD4+ T cells." (PMID 31694706, 2019). "Interestingly class II HER2-DC1 led to both increased CD4 and CD8 T cells in the tumor microenvironment while class I peptides typically resulted in only increased CD8 T cells." (PMID 31475002, 2019). "Conversely, percentages of CD62Llow CD44high effector CD4+ and CD8+ T cells were significantly increased after treatment, suggesting that erlotinib treatment leads to increased effector T cells in the tumor microenvironment." (PMID 31291990, 2019). "Analysis of the immune infiltrates from tumor and lymph nodes post treatment revealed an expansion of IFN-γ producing CD4 T cells (Th1) and the neutralization of IFN-γ abolished the anti-tumor effect of checkpoint blockade suggesting the key role for these cells and this cytokine." (PMID 31824850, 2019). "CD4+ T cells, CD8+ T cells, and NK cells play important roles in anti-tumor immunity." (PMID 30781674, 2019). "Indeed, on the one hand, tumor-derived EVs carry FasL and TRAIL molecules and can directly induce apoptosis of DCs or effector CD4+ and CD8+ T-lymphocytes." (PMID 31680949, 2019). "Further, the infiltrated CXCR5+CD4+ T cells was demonstrated to be significantly less in HCC tumor regions than that of non-tumor regions." (PMID 31507621, 2019). "CD4+ T cells play an important role in the TME and can contribute to an anti-tumor immune response." (PMID 31681561, 2019). "Prophylactic transfer of Rnf5−/− microbiota was sufficient to delay tumor growth, as well as to enhance infiltration of tumor-specific CD45+, CD4+, CD8+ T cells and increase cytokine production, supporting a role for the Rnf5−/− microbiota in mediating antitumor effects." (PMID 30940817, 2019).